IDH1 (isocitrate dehydrogenase (NADP(+)) 1)
Diseases named in the same sentence as IDH1 in open-access papers (continued):
Sharing a sentence is not in itself a finding about the gene and the disease.
tumor (continued). "Analysis of mutational signatures in the 100KGP cohort (n = 52) revealed nine active signals, with SBS1, SBS5, and SBS8 being ubiquitous and most prominent across IDH1, IDH2, and IDHwt tumours." (PMID 36042521, 2022). "Furthermore, NFIA was found to be upregulated in CIC‐mutant cells compared with CIC‐wild type cells in a single‐cell gene expression analysis of a primary ODG, indicating that the increased NFIA expression that we observed in CIC‐KO (IDH1‐R132H) cells may be relevant in a primary tumour context." (PMID 34767259, 2022). "IDH1, IDH2 gene was a potential tumor early diagnosis, prognosis evaluation and target therapeutic marker genes." (PMID 36618415, 2022). "Since we only studied tumor somatic alterations and did not perform germline DNA studies or conduct single-cell analysis, we are unable to demonstrate if the two co-occurring mutations in IDH1 in this patient belonged to a homozygous clone or to two different clones." (PMID 35740557, 2022). "In a study, the level of 2-hydroxy glutarate when checked by mass spectroscopy showed an increase in its concentration, indicating direct correlation with IDH1 and IDH2 that in turn indicates the presence of the tumor." (PMID 36185622, 2022). "Together, these data imply further differences in the rate of evolution from G2/3 to DD CS across IDH1, IDH2, and IDHwt tumours." (PMID 36042521, 2022). "In addition, IDH1 may affect the tumor microenvironment and immune cell infiltration in PRAD." (PMID 35132321, 2022). "A synthetic lethal interaction between mutant IDH1/2 and members of the BCL-2 family was first reported in AML tumor models." (PMID 35267433, 2022). "Mice were vaccinated with the IDH1 peptide, triggering an MHC-II-like effect and thereby an anti-tumor response." (PMID 34885082, 2021). "We observed that IDH1-R132H inhibition used in combination with SOC and anti-PD-L1 immune checkpoint blockade increased the frequency of tumor-specific cytotoxic CD8+ T cells and IFN-γ release within the TME." (PMID 34168976, 2021). "We verified the inhibitory effect of IDH1 and its substrate α-KG on RCC by regularly measuring the tumor size and weight of tumor-bearing mice." (PMID 33867843, 2021). "But in patients with IDH1 wild type, the OS (p = 0.05) of patients with tumor-SVZ distance >10 mm was significantly better than in patients with tumor-SVZ distance from 0 to 10 mm." (PMID 34490090, 2021). "Their prevalence is different according to the cancer type since it was found that IDH1 has higher incidence rate than IDH2 in brain cancers, while in AML they are equally common, likely reflecting the differential tumour metabolic needs." (PMID 34070384, 2021). "Both IDH1 and IDH2 are overexpressed in several types of tumours, decreasing ROS production and increasing concomitantly NADPH." (PMID 34880756, 2021). "In view of the important roles of mutant IDH1, IDH2 and their products in tumorigenesis and progression, another strategy of tumor therapy is to target mutant enzymes and products." (PMID 33981605, 2021). "Several authors have extensively demonstrated the expression of GBM markers, such as EGFR, MGMT, IDH1 R132H, and ATRX, in tumor cells using IHC, which is much more applicable for neuropathology routine." (PMID 33673104, 2021). "Therefore, IDH1-related tumor metabolism may be a target for the treatment of 5FU-resistant CRC." (PMID 34234856, 2021). "Combined single-cell RNA and T cell receptor sequencing showed that tumour-infiltrating CD40LG+ and CXCL13+ T helper cell clusters in a patient with pseudoprogression were dominated by a single IDH1(R132H)-reactive T cell receptor." (PMID 33762734, 2021). "Next, we sought to further probe the mechanistic basis for enhanced tumor cell kill induced by AZD6738 and olaparib combination treatment in IDH1/2-mutant cells." (PMID 34027408, 2021).
tumor (continued). "We conducted a retrospective review in newly diagnosed, IDH1 wild-type GBM patients, comparing SupTR with gross total resection (GTR), in which only CE tumor tissue was resected." (PMID 34267303, 2021). "Applying single-cell chromatin accessibility profiling (scATAC-seq) across four primary adult GBM tumors (3797 cells), wild type for both IDH1 and IDH2, revealed seven to nine accessibility modules in each tumor based on unsupervised clustering." (PMID 33427645, 2021). "This study, and others, based on bulk tumour or single-cell sequencing have identified molecular markers such as, methylation status of MGMT promoter and w/t IDH-1 status that have been widely explored as prognostic biomarkers for therapy responsiveness." (PMID 34490102, 2021). "Our experiments, based on a wild-type IDH1/2 GBM cell line model, suggest a more direct role of Tau in tumor cell properties." (PMID 34830972, 2021). "A total of two patients with isocitrate dehydrogenase 1 (IDH1)-mutant tumors and one with a DNA polymerase epsilon (POLE)-mutant tumor reached a survival ≥ of 16 months." (PMID 33810532, 2021). "The work utilizes digital pathology images and four key molecular features (IDH1/2, 1p/19q, ATRX, and MGMT) to obtain improved tumor classification and stratification accuracy." (PMID 34277415, 2021). "While mutant IDH1 can reduce a-ketoglutarate to D2HG, which results in the accumulation of D2HG in tumor microenvironment." (PMID 34220689, 2021). "We speculate that the infratentorial lesion may be a metastatic, higher grade lesion arising from the supratentorial mass, and that the non-canonical IDH1 mutation marked sub-clones with increased tumor invasiveness and/or chemoresistance which diverged early on in tumorigenesis." (PMID 34587990, 2021). "Reductive carboxylation of glutamine mediated by IDH1 facilitated the transfer of reducing power, in the form of NADPH, from the cytosol to the mitochondria to help detoxify ROS generated in tumor cells grown in spheroids." (PMID 33808242, 2021). "IDH1 and IDH2 also catalyze the reductive carboxylation and support tumor cells growth with defective mitochondria." (PMID 33028807, 2020). "All patients had neuropathologically confirmed GBM with an expression of wild-type isocitrate dehydrogenase 1 (IDH-1) and wild-type ATRX and underwent resection of their tumor with 5-ALA guidance." (PMID 32904996, 2020). "Anatomical scans between day 23 and 33 of treatment revealed successful tumor-take in 10/10 animals for LNT-229, in 8/8 for LNT-229 IDH1-R132H, and in 7/7 for GL261." (PMID 33138036, 2020). "Concordantly, IDH1 silencing in a DLBCL cell line decreased αKG and GSH production, with subsequent ROS increase and tumor growth reduction." (PMID 31010244, 2019). "The IDH1 mutant also seems to induce the NF-κB pathway in an HIF1-α dependent manner, regulating tumor cell proliferation." (PMID 30708988, 2019). "IDH305 inhibited 2-HG production and tumor cell proliferation with an IC50 = 24 nM, and showed an anticancer activity in IDH1/132H–mut cells in preclinical studies." (PMID 30857299, 2019). "The circulating NRAS mutations split the metabolic groups, and the IDH1 mutation was only found in Patient 3, however, it cannot be ruled out that a more detailed genomic analysis of the tumour itself could have revealed additional mutations which correlated with the metabolic changes observed." (PMID 31795195, 2019).
tumor (continued). "For example, in a murine model for LGG, the introduction of mutant IDH1 or treatment with 2HG reduced protein levels of CXCL10 likely through decreased production of STAT123, and suppressed the accumulation of T cells at tumor sites." (PMID 31601888, 2019). "Among several IDH1/2 mutant inhibitors, AG-120, AG-881, ML309, GSK321, and GSK864 exhibited remarkable anti-tumor activity, showing a significant histone and DNA demethylation activity in vitro." (PMID 31366176, 2019). "His GBM tumor tissue demonstrated O6-methylguanine-DNA methyltransferase (MGMT) promoter methylation, wild-type isocitrate dehydrogenase 1/2 (IDH1/2) and amplification of the epidermal growth factor receptor (EGFR) gene." (PMID 30766509, 2019). "In skin epidermal JB6 P+ cells, a well-established model for tumor promotion, WA inhibited tumor promoter TPA-induced decreases in IDH1 activity and mitochondrial function." (PMID 31308852, 2019). "A small proportion of initial tumours had SNVs in the G-protein gene, GNAS (5%; 2/38), IDH1/2 (5%; 2/38), and the Rb-specific cell-cycle regulation genes CDK6 and RB1 (5%; 2/38)." (PMID 32082376, 2019). "In the present study, we compared clinical data and conventional MRI data between IDH1-mutant and IDH1-wild type GBM patients and found significant differences in age, the tumor location, and the tumor size between the two groups." (PMID 31275753, 2019). "The percentage of each dynamic 18F-FET TAC within tumors and other conventional 18F-FET PET parameters (maximum and mean tumor-to-brain ratios [TBRmax and TBRmean], time-to-peak [TTP] and slope) was compared between wild-type and IDH1 mutant tumors." (PMID 29953478, 2018). "Further development of compound 1 yielded AGI-5198 (Compound 2), the first reported mutant IDH1 inhibitor that showed robust in vivo reduction of D-2HG levels in U87 R132H and HT1080 R132C cell lines and in U87 R132H tumor xenograft model." (PMID 29439493, 2018). "Overexpression of IDH1 was reported in non-small cell lung (NSCL) cancer, both in plasma and tumor tissues." (PMID 30153799, 2018). "IDH1, a NADP-dependent enzyme which involves in the control of oxidative cellular damage, was identified as a tumor suppressor since its inactivation plays a vital role in tumorigenesis." (PMID 30153799, 2018). "This yielded four patients with an IDH1-mutant, 1p/19q-codeleted tumor, seven patients with an IDH1-mutant, 1p/19q-non-codeleted tumor, and six patients with most likely an IDH-wildtype tumor." (PMID 30094719, 2018). "Interestingly, some researchers hypothesized the tumor suppressor roles of IDH1 and 2 based on their function to produce 2KG that in turn would be utilized by dioxygenases e.g. PHD to inactivate tumorigenic proteins like Hif1α (will be discussed in details in the following sections)." (PMID 28785398, 2017). "Mutant IDH-1, which is G-CIMP-positive, has better prognosis and treatment response that is commonly seen in grade 2 and 3 tumor, thus representing secondary GBM." (PMID 28630875, 2017). "Patient 5, a 69 year-old man with a recurrent GBM (IDH1/2 wild type, methylated MGMT promoter), had tumor progression on a clinical trial consisting of IMRT/TMZ, then TMZ and vorinostat (a histone deacetylase inhibitor)." (PMID 29113409, 2017).
tumor (continued). "Nevertheless, nCBV of IDH1 WT rats increased after bevacizumab treatment, which seems to be correlated to excreted glutamate by BCAT1 activity fueled to the tumor cell for proliferation, suggesting that it induces resistance." (PMID 27626306, 2016). "Immunohistochemistry demonstrates tumor cells were positive for GFAP, OLIG2, SOX2, IDH1(R132H) and a MIB1 proliferation index of >30 %." (PMID 26817999, 2016). "RNA interference in IDH1 inhibits the proliferation of NSCLC cells and suppresses tumor growth in a xenograft model." (PMID 27863386, 2016). "A tumor sample with an MAF of 40% was selected, and its lysate was mixed with another lysate from a tumor with wild-type IDH1 such that the MAF was decreased stepwise from 40% to 20, 10, 5, 2, and 1%." (PMID 27877908, 2016). "By the log rank test, low IDH1-R132H expression (P=0.001), preoperative CEA level (P<0.001), and tumor stage (P<0.001) all correlated negatively with OS." (PMID 27655638, 2016). "In IDH1 mt patients, TTR was increased along with smaller residual tumor volumes at follow-up MRI (HR 1.01; p = 0.03)." (PMID 27344556, 2016). "Here, given the known role of BCAT1 in tumor cell proliferation and invasiveness, we investigate the bevacizumab resistance increased by BCAT1 expression in IDH1 WT GBM rat models using DSC perfusion MRI." (PMID 27626306, 2016). "In addition to patient age, IDH1 status may be predicted from the imaging features of the tumour." (PMID 25849605, 2015). "Consistent with this premise, tumor cells most sensitive to these agents exhibit over expression of TCA-related discriminating genes, IDH3A, IDH1, IDH3G, ACO2 and ACLY." (PMID 23056181, 2012). "The T dispersion ratios explored did not yield any significant distinction between IDH1‐mutant and ‐wild‐type tumours." (PMID 41436375, 2026). "Molecular profiling of Western intrahepatic iCCA cohorts reveals IDH1 genomic alterations in 13% of cases and FGFR2 fusion events in 8%–14%.32, 33, 34 In this study, we detected an FGFR2 fusion in both tumor tissue and matched bile samples, while it was undetectable in plasma cfDNA." (PMID 41399682, 2025). "Immunohistochemistry showed positive staining for IDH1 R132H, indicating an IDH-mutant tumor." (PMID 41140994, 2025). "Though molecular analyses were not obtained for our patient’s initial tumor, molecular analyses obtained from his re-resection confirmed that his tumor harbors the canonical IDH1-R132H and codeletion of 1p/19q." (PMID 39857783, 2025). "Significant increases in gene expression of GFAP (4-fold), a type III intermediate filament in astrocytes, and IDH1 (5-fold) were observed in tumour samples, with no observed changes in IDH2 expression." (PMID 41034696, 2025). "Although IDH1/2-mutated tumors and those with 1p/19q codeletion are no longer classified as GBM, these findings highlight the potential of CSF for detecting tumor-related DNA alterations and improving differential diagnosis." (PMID 40427551, 2025). "Our limited power in the WT IDH1 HT1080∗ tumors due to lack of tumor formation in 7/9 mice likely complicated analysis, as one of the two WT tumors was unusually large." (PMID 40188944, 2025). "The tumor cells were positive for GFAP but negative for IDH1 on IHC; accordingly, a diagnosis of metastatic HGG was made." (PMID 40585465, 2025).
tumor (continued). "For instance, the presence of small regions of enhancement, a larger non-enhancing tumor component, well-defined tumor margins, and T1-weighted hypointense areas with suppressed FLAIR signals within necrotic regions are indicative of an IDH1 mutation." (PMID 39768232, 2024). "Diffuse low‐grade gliomas (LGG) MAPK pathway‐altered tumours are associated with almost all MAPK pathway‐associated anomalies, and are presented without any IDH1/2 and H3F3A mutations." (PMID 38299304, 2024). "MPA treatment markedly impaired tumor volume, weight, and proliferation in the IDH1T77A tumor‐bearing group; however, in IDH1 T77D mice, no significant reduction in tumor growth was observed." (PMID 38582508, 2024). "In none of the IDH1-altered tumor samples, oligodendroglial features or 1p/19q-codeletion were present." (PMID 38717379, 2024). "Among other immunostains not shown, ATRX nuclear expression was retained in all tumor cells, and none of the tumor cells were positive for IDH1 R132H mutant protein, napsin, NKX3.1, CD45, synaptophysin, INSM1, SOX10 protein, p40, CDX2 protein, PSAP, or PSA." (PMID 38845695, 2024). "In addition, enzymatic properties of mutant IDH1 inhibited IFNγ-TET2 signaling and promoted immune escape and tumor viability in cholangiocarcinoma." (PMID 38581001, 2024). "The mIDH1 inhibitors inhibit tumor growth by blocking mutant IDH1 enzyme activity, reducing 2-HG production and restoring normal epigenetic regulation." (PMID 39512821, 2024). "High 2-HG in IDH1 MT tumors increases the consumption of NADPH and limits the availability of NADPH for de novo lipogenesis, raising the possibility that such tumor cells could be selectively vulnerable to FASN inhibition in IDH1 MT tumors." (PMID 39149696, 2024). "However, the acetylation of these proteins has been confirmed to play a role in the regulation of tumor development, including SDHA, IDH1, and HMGB1." (PMID 38831454, 2024). "Within FFPE sections, tumor-rich ROIs were selected that either had a high T cell number (up to 94 T cells per region) or no T cells according to immunofluorescent tagging of tumor cells (IDH1-R132H), leukocytes (CD45), and T cells (CD3)." (PMID 36590163, 2023). "Treatment of mouse CD8 T cells with IDH1 and NADP+ enhanced binding to tumor pMHC-I." (PMID 37161052, 2023). "The growth of subcutaneous sarcomas carrying either IDH1 WT or IDH1R132H was investigated following preventative vaccination: tumours positive for IDH1R132H grew more slowly than those expressing the WT protein, showing the efficacy of the anti-tumour therapy." (PMID 37296846, 2023). "MMR protein expression in tumor cells was present with a score of 2 to 3, independent of MGMT status (promoter methylation and protein expression), sex, age, IDH1 mutation status or treatment." (PMID 37047153, 2023). "This study aimed to identify the levels of 5-hmC, 5-mC, TETl, TET2, TET3, IDH1, and IDH2 in tumor and the adjacent tissues, so as to explore whether the 5-hmC is decreased in HBV-related HCC tissues and, if possible, to explore the associated mechanism." (PMID 37266610, 2023). "Moreover, one patient, with an IDH1 wild-type and MGMT unmethylated tumor received a total of six doses of pembrolizumab with overall stable disease." (PMID 37188783, 2023).